API5 (apoptosis inhibitor 5)
Diseases named in the same sentence as API5 in open-access papers (continued):
Sharing a sentence is not in itself a finding about the gene and the disease.
colorectal cancer (2 papers, 2015 to 2016). A primary or metastatic malignant neoplasm that affects the colon or rectum. "It has also been shown that Api5 is expressed in various human tumors including colorectal cancer." (PMID 25881233, 2015).
diabetes (2 papers, 2010 to 2016). "The API5 gene is involved in many human diseases including diabetes and cancers." (PMID 27994956, 2016). "API5, EDIL3, BFSP2, HNMT, and SCYL1BP1 were also among the top signals from the single-marker analysis within their associated region, but there is no clear connection currently between these genes and diabetes or its complications." (PMID 20871662, 2010).
lupus (2 papers, 2022 to 2023). "API5 under-expression is linked to the pathogenesis of systemic lupus erythematosus (SLE) via apoptosis, whereas overexpression is linked to the progression of various cancers." (PMID 36005137, 2022).
B cell chronic lymphoid leukemia (1 paper, 2013). "Interestingly, Api5 expression is deregulated in multiple cancer cell lines, including various human cancers: cervical or prostate, Non Small Cell Lung Cancer (NSCLC), and B cell chronic lymphoid leukemia (B-CLL)." (PMID 23940755, 2013).
colorectal tumors (1 paper, 2014). "They detected API5 protein expression in biopsies of lung (23%, 3/13) and colorectal tumors (33%, 9/27)." (PMID 25070070, 2014).
Crohn disease (1 paper, 2024). A gastrointestinal disorder characterized by chronic inflammation involving all layers of the intestinal wall, noncaseating granulomas affecting the intestinal wall and regional lymph nodes, and transmural fibrosis. "Correlative to this observation, histological analyses of terminal ileum of patients with Crohn’s disease with Atg16l1 deficiency indicated a reduction in API5+ γδ IEL cells." (PMID 38275765, 2024).
heart failure (1 paper, 2022). Inability of the heart to pump blood at an adequate rate to meet tissue metabolic requirements. "Here we used whole-exome sequencing and bioinformatics on human patient data to identify 3 genes (API5, HSPB7, and LMO2) suggestively associated with heart failure that were also predicted to play a broader role in disease aetiology." (PMID 35548346, 2022). "We identified a subset of three genes (API5, HSPB7, and LMO2) predicted to play a broader role in heart failure aetiology, and undertook in vivo phenotypic assessment in zebrafish." (PMID 35548346, 2022).
ischemic cardiomyopathies (1 paper, 2022). "The most pronounced changes in cardiac and blood API5 expression included downregulated expression in association with myocardial infarction, and upregulated heart API5 expression in association with ischemic and non-ischemic cardiomyopathies." (PMID 35548346, 2022).
liver cancer (1 paper, 2024). An epithelial or non-epithelial malignant neoplasm that arises from the liver. "As the silencing of API5 promotes ABT-263-induced DNA damage, it is possible that API5 could function as a regulator of the DNA repair machinery, as its association with the chromatin remodeler ALC1 (amplified in liver cancer 1), which plays a key role in DNA repair, suggests." (PMID 38275765, 2024).
lung carcinoma (1 paper, 2012). "In this cluster, NT5C2, API5, CPN, PRKAR1A and COPB1 were fully down-regulated in lung cancer." (PMID 23122428, 2012).
osteosarcoma (1 paper, 2021). A usually aggressive malignant bone-forming mesenchymal neoplasm, predominantly affecting adolescents and young adults. "Similar result was also observed in the human osteosarcoma cell line, Saos-2, where ectopic expression of Api5 decreased E2F1-mediated apoptosis in E2F1 over-expressing cells without affecting its transcriptional activity." (PMID 34385547, 2021). "In osteosarcomas, studies have shown Api5 to inhibit E2F1 as well as Acinus-mediated apoptosis." (PMID 34385547, 2021).
squamous cell carcinoma (1 paper, 2025). A carcinoma arising from squamous epithelial cells. "In squamous cell carcinoma, miR-483-3p sensitized cells to apoptosis by targeting anti-apoptotic genes such as API5, BIRC5, and RAN." (PMID 40537919, 2025).
squamous cell lung carcinoma (1 paper, 2014). A carcinoma arising from squamous bronchial epithelial cells. "Sasaki and colleagues reported that an increased API5 mRNA expression was detected in 12.7% (12/94) of the non-small cell lung cancer (NSCLC) biopsies and its presence was correlated with poor survival, especially in patients with squamous cell lung cancer." (PMID 25070070, 2014).
tumor (21 papers, 2013 to 2024). "API5 has emerged as a key player in the context of cancer as its overexpression has been associated with aggressive tumor behavior, resistance to treatment, and poor prognosis." (PMID 38275765, 2024). "For the XBC-S chemosensitive TNBC xenograft model, anti-API-5 peptide induced tumor necrosis associated with a decrease in microvessel density, but to a lesser degree than in XBC-R ([20% versus 45% of necrosis)." (PMID 31762939, 2019). "This vascular effect of anti-API-5 peptide was associated with a 2-fold decrease in numbers of CD31-expressing murine vessels (4% in treated mice versus 8% in untreated tumor xenografts, p = 0.01)." (PMID 31762939, 2019). "Finally, Api5 overexpression has been associated with tumor progression in patients with cervical cancer." (PMID 28881748, 2017). "While it may not have yet the same level of notoriety as some other cancer-associated proteins, API5 has garnered increasing attention in the cancer field in recent years, as elevated API5 levels are often associated with aggressive tumor behavior, resistance to therapy, and poor patient prognosis." (PMID 38275765, 2024). "Another mechanism by which API5 contributes to tumor progression is through the induction of tumor immune escape." (PMID 38275765, 2024). "Morris and colleagues initially noted that the depletion of API5 was specifically lethal to tumor cells with deregulated E2F1." (PMID 38275765, 2024). "Shortly after, a crucial role for API5 in tumor cells’ sensitivity to anticancer drug was demonstrated by different groups." (PMID 38275765, 2024). "When the Api5 KD cells (MCF10CA1a) were injected into the flanks of mice, they formed tumours, although the size was smaller when compared to MCF10CA1a control cells." (PMID 37095445, 2023). "It was observed that while the MCF10CA1a control tumours continued to grow, Api5 KD MCF10CA1a tumours stopped growing and maintained a size similar to that of week 2 tumours." (PMID 37095445, 2023). "When these Api5 KD MCF10CA1a cells were injected into the flanks of athymic mice they formed tumours, although the tumour volume was significantly reduced compared to the control MCF10CA1a cells." (PMID 37095445, 2023). "Using a murine probe, we assessed API-5 mRNA expression in CD105-positive tumor endothelial cells sorted from the two xenograft models." (PMID 31762939, 2019). "In XBC-R xenografts treated with anti-API-5 peptide, we found a 5-fold increase in tumor necrosis areas at day 28 compared to untreated tumor xenografts (45% versus 18%, p < 0.01)." (PMID 31762939, 2019). "We also found a direct effect of anti-API-5 peptide on human tumor cells with proliferation inhibition in treated tumor xenografts at day 28 (30% of Ki67-expressing cells in treated mice versus 70% in untreated mice, p = 0.01)." (PMID 31762939, 2019). "In our study, higher API-5 expression in tumor endothelial cells was in line with the considerable anti-angiogenic tissue effect that we observed after 4 weeks of treatment with anti-API-5 peptide." (PMID 31762939, 2019). "In our study, after 28 days of treatment of patient-derived TNBC xenografts with anti-API-5 peptide administered intraperitoneally, we showed direct effects on both tumor cells and endothelial cells within the tumor, with a major anti-angiogenic effect." (PMID 31762939, 2019). "In a recent pre-clinical study, anti-API-5 peptide administered intraperitoneally for seven days in mice xenografted with human melanoma cancer cell lines was mainly distributed in the tumor, the liver, the kidney, and the spleen." (PMID 31762939, 2019). "Since API-5 is involved in resistance to apoptosis, we postulated that TNBC chemoresistance was partly due to tumor resistance to apoptosis and thus to API-5 expression before any treatment." (PMID 31762939, 2019). "At a concentration of 2.4 mg/kg, anti-API-5 peptide inhibited tumor growth in the XBC-R chemoresistant xenograft model." (PMID 31762939, 2019).
tumor (continued). "When we assessed API-5 expression using simple peroxidase immunostaining, API-5 was mainly expressed in tumor endothelial cells." (PMID 31762939, 2019). "In our study, anti-API-5 peptide induced an anti-tumor effect in the two patient-derived TNBC xenograft models we used." (PMID 31762939, 2019). "In vivo, xenografted MCF7 cells knockdown for Api5, displayed a strong reduction in tumor growth indicating its tumorigenic properties." (PMID 28881748, 2017). "Collectively, besides its ability to confer anti-apoptotic property to cancer cells, API5 is also able to turn tumor cells into CSC-like cells by regulating NANOG expression." (PMID 28092370, 2017). "To address if Api5 influenced tumor growth in vivo, we next injected subcutaneously into the anterior flanks of female nude mice the MCF7 sh0 control cell line and the shApi5 cell line." (PMID 28881748, 2017). "Since compact spheroid formation has been suggested to correlate with aggressiveness of tumors, these results suggest that Api5 had tumor-promoting effects in MCF7, T47D and in a lesser extent in MDA-MB-231 cells independently of estrogen stimulation." (PMID 28881748, 2017). "In particular, apoptosis inhibitor 5/antiapoptosis clone-11 (Api5/Aac11) is known to suppress a specific mode of apoptosis in mammalian cells and thought to function in tumor development." (PMID 25881233, 2015). "In this context, API5 expression has been reported in a number of tumor cell lines, and, subsequently, API5 elevated mRNA and protein expression levels were confirmed in a wide variety of transformed cell lines." (PMID 25070070, 2014). "Furthermore, using other tumor settings, Song and colleagues demonstrated that API5 enhanced MMP-9 expression through an ERK-dependent regulation of activator protein 1 (AP-1)." (PMID 38275765, 2024). "In line with this hypothesis, API5 expression has been demonstrated to contribute to tumor invasion and metastases in various cancer settings." (PMID 38275765, 2024). "Finally, a substantial number of studies have shown that API5, which was initially identified for its antiapoptotic function, is critically involved in tumor survival and resistance to chemotherapeutic drugs." (PMID 38275765, 2024). "Indeed, in a very interesting study, the group led by Tae Woo Kim demonstrated that API5 plays key roles in both tumor progression and immunity." (PMID 38275765, 2024). "Therapeutic targeting of API5 could therefore represent a potential treatment option for cancer through tumor immune escape." (PMID 38275765, 2024). "Elevated expression of Api5 in tumour tissues supports the possibility that Api5 may be a tumour promoter in breast malignancies." (PMID 37095445, 2023). "Therefore, the anti-API5 peptide targeting API-5 promotes the apoptosis of TNBC tumor cells by preventing the API-5/acinar interaction and reactivating the caspase-3 pathway." (PMID 37691919, 2023). "Early reports started pointing at the possible tumour promoting role of Api5." (PMID 37095445, 2023). "The increased expression of API5 in tumor cells may contribute to resistance to cisplatin drug therapy." (PMID 38143869, 2023). "We showed that both tumor cells and endothelial cells expressed API-5." (PMID 31762939, 2019). "Anti-API-5 also induced a decrease in tumor cell proliferation (by about 1.75)." (PMID 31762939, 2019). "Notably, a larger tumor size of cervical neoplasia had a significant correlation with triple-positive API5+/FGF2+/NANOG+ expression." (PMID 28092370, 2017). "Therefore, the ability to down-regulate API5 can contribute to the apoptotic activity of miR-203 and its effects on tumor cells." (PMID 25004126, 2014). "API5 protein expression was exclusively identified in the nucleus of tumor cells while the expression of pERK1/2 was detected in the cytoplasmic and nuclear of the tumor cells." (PMID 25070070, 2014).
tumor (continued). "Moreover, Api5 depletion has been shown to be lethal to tumor cells under low serum stress, whereas Api5 overexpression promotes cell growth and migration." (PMID 23940755, 2013). "Interestingly, the expression of an acetylation-deficient mutant of API5 (K251A) did not protect tumor cells from apoptosis induced by serum deprivation." (PMID 38275765, 2024). "Indeed, the silencing of API5 in various cell lines sharply increased tumor cells’ sensitivity to chemotherapeutic drugs such as etoposide, camptothecin, or cisplatin, whereas API5-forced expression endowed cancer cells with enhanced resistance to these agents." (PMID 38275765, 2024). "Thus, as for ERα and PR, the presence of Api5 is necessary for tumor growth." (PMID 28881748, 2017). "Considering the aggressive nature of the defects leading to eBL development, downregulated miR-10a-5p could also promote the hyperactivation of API5 (apoptosis inhibitor 5), an apoptosis inhibitory protein, which renders tumor cells resistant to T cell initiated apoptosis." (PMID 28400759, 2017). "In fact, DAMP proteins binding to TLR4 (e.g., HMGB1, S100, HSPs, API5, and RPS3) have been used as adjuvants for DC-based vaccines, affecting tumor prevention, treatment, and survival." (PMID 33299138, 2020). "In particular, API-5 expression was higher in the XBC-R model, both for mRNA and for protein, and this was true in both tumor cells and tumor endothelial cells." (PMID 31762939, 2019). "We then wondered if there was also a differential expression of API-5 in murine tumor endothelial cells of the XBC-R and XBC-S tumor xenografts." (PMID 31762939, 2019). "When we assessed human API-5 mRNA expression in tumor cells (n = 5 for each) of the XBC-S and XBC-R models, we found that API-5 was significantly over-expressed in XBC-R tumor xenografts (RQ = 1.4, p < 0.05)." (PMID 31762939, 2019). "Overall, our results showed higher levels of expression of API-5 in chemoresistant TNBC xenografts, for both protein and mRNA, particularly in tumor endothelial cells." (PMID 31762939, 2019). "The apoptosis inhibitor-5 (API5), anti-apoptosis protein, is considered a key molecule in the tumor progression and malignant phenotype of tumor cells." (PMID 25070070, 2014). "The Api5 OE cells did not form tumours (data not shown) suggesting that overexpression of Api5 is capable of partially transforming breast epithelial cells grown as acinar cultures with diminished tumorigenic potential." (PMID 37095445, 2023). "This is coherent with the fact that hypoxia within a tumor can increase API-5 expression, and that targeting API-5 could reverse resistance to apoptosis in the tumor." (PMID 31762939, 2019). "An analysis of biopsies from 78 women with locally advanced TNBC before chemotherapy showed that API-5 was more markedly expressed in tumor endothelial cells of chemoresistant tumors as opposed to non-resistant tumors." (PMID 31762939, 2019). "At the molecular level we show that Api5 co-localizes with ERα and interacts directly with ERα DNA Binding Domain (C) domain through the LXXLL motif and that down regulation of this factor can suppress tumor growth in vivo." (PMID 28881748, 2017). "However, the mechanism of anti-API-5 was different in the chemosensitive model, since the peptide did not induce an increase in apoptotic tumor cells, in contrast to the chemoresistant model." (PMID 31762939, 2019). "This difference in proliferation between Api5 positive and negative cells may be an explanation for the difference in tumor size observed after 7 weeks." (PMID 28881748, 2017). "The relatively high number of Api5 expressing cells in the shApi5 tumors (only 31.7% of the tumor is Api5 negative) might be the consequence of a possible bystander effect." (PMID 28881748, 2017).
tumor (continued). "In addition, API5 expression was an independent prognostic factor for overall and disease-free survival after adjusting for well-known prognostic parameters including FIGO stage, cell type, tumor grade, tumor size and LN metastasis." (PMID 25070070, 2014). "Furthermore, tumor cells expressing API5 K251A in an API5 knockdown background could not survive while in culture." (PMID 38275765, 2024). "However, Api5 OE cells did not form tumours in athymic mice." (PMID 37095445, 2023). "In order to block API-5 expression by a peptide in patient-derived TNBC xenograft models, the maximum tolerated dose of anti-API-5 peptide was assessed in nude mice without any tumor." (PMID 31762939, 2019).